CD33 (CD33 molecule)
Description:
Sialic-acid-binding immunoglobulin-like lectin (Siglec) that plays a role in mediating cell-cell interactions and in maintaining immune cells in a resting state. Preferentially recognizes and binds alpha-2,3- and more avidly alpha-2,6-linked sialic acid-bearing glycans. Upon engagement of ligands such as C1q or syalylated glycoproteins, two immunoreceptor tyrosine-based inhibitory motifs (ITIMs) located in CD33 cytoplasmic tail are phosphorylated by Src-like kinases such as LCK. These phosphorylations provide docking sites for the recruitment and activation of protein-tyrosine phosphatases PTPN6/SHP-1 and PTPN11/SHP-2. In turn, these phosphatases regulate downstream pathways through dephosphorylation of signaling molecules. One of the repressive effect of CD33 on monocyte activation requires phosphoinositide 3-kinase/PI3K.
Synonyms: Siglec-3; SIGLEC3; p67; FLJ00391; CD33rSiglec
Tractability: Small molecule: a structure with a bound ligand is known. Antibody: a drug acting on it is in phase 2 or 3 trials; UniProt places it where antibodies can reach, with high confidence; its Gene Ontology location is reachable by antibodies, with high confidence; UniProt predicts a signal peptide or a membrane-spanning region; the Human Protein Atlas places it where antibodies can reach. PROTAC: ubiquitination databases record sites on it; its protein half-life has been measured. Other modalities: an approved drug acts on it.
Target class: Surface antigen
Gene: Protein-coding gene on chromosome 19 (51,217,033 to 51,243,860, forward strand). Ensembl gene ENSG00000105383.
Subcellular location: Cell membrane (Isoform CD33M); Peroxisome (Isoform CD33m)
Subcellular location (Human Protein Atlas): Plasma membrane; Cytosol
Pathways (Reactome):
Immune System: Immunoregulatory interactions between a Lymphoid and a non-Lymphoid cell; Neutrophil degranulation
Disease: Dengue Virus Attachment and Entry
Gene Ontology:
Molecular function: protein binding; protein phosphatase binding; protein tyrosine phosphatase activator activity; sialic acid binding; signaling receptor activity
Biological process: cell-cell adhesion; Fc-gamma receptor signaling pathway; immune response-inhibiting signal transduction; negative regulation of interleukin-1 beta production; negative regulation of interleukin-8 production; negative regulation of monocyte activation; negative regulation of tumor necrosis factor production; positive regulation of protein secretion; cell adhesion; cell-cell signaling; negative regulation of cell population proliferation; signal transduction
Cellular component: external side of plasma membrane; Golgi apparatus; peroxisome; plasma membrane; specific granule membrane; tertiary granule membrane
Genetic constraint (gnomAD): Loss-of-function variants: 26 observed, 33.65 expected, observed/expected ratio (o/e) 0.77, 90% interval 0.56 to 1.07. The upper end of that interval is the gene's LOEUF score, 1.07, which puts it in group 4 of 6, group 1 being the genes least tolerant of losing a copy. Missense variants: 407 observed, 464.49 expected, observed/expected ratio (o/e) 0.88, 90% interval 0.81 to 0.95. Synonymous variants: 176 observed, 187.68 expected, observed/expected ratio (o/e) 0.94, 90% interval 0.83 to 1.06.
Homologues: Orthologues: chimpanzee CD33 (96% identical), macaque CD33 (86% identical), tropical clawed frog siglecl2 (26% identical), tropical clawed frog siglecl2 (25% identical), tropical clawed frog siglecl1 (23% identical), tropical clawed frog siglecl1 (15% identical). Paralogues in human: SIGLEC6 (56% identical), SIGLEC8 (54% identical), SIGLEC9 (53% identical), SIGLEC7 (53% identical), SIGLEC5 (51% identical), SIGLEC12 (49% identical), SIGLEC10 (42% identical), SIGLEC14 (41% identical), SIGLEC11 (38% identical), SIGLEC1 (27% identical), MAG (22% identical), SIGLEC15 (22% identical), and 4 more.
Diseases named in the same sentence as CD33 in open-access papers:
CD33 is named in the same sentence as 217 diseases in open-access papers, as found by Europe PMC text mining. Sharing a sentence is not in itself a finding about the gene and the disease. The quoted sentences say what the papers report.
acute myeloid leukemia (347 papers, 2009 to 2026). Acute myeloid leukemia (AML) is a group of neoplasms arising from precursor cells committed to the myeloid cell-line differentiation. "For instance, gemtuzumab ozogamicin, which targets CD33 in acute myeloid leukemia, frequently causes ALT/AST elevations, despite CD33 being absent in hepatic tissue." (PMID 40006625, 2025). "In the haematological setting, a dual CAR approach has been developed to mitigate the on-target/off-tumour toxicities associated with targeting CD123 and CD33 in acute myeloid leukaemia (AML)." (PMID 39596267, 2024). "Recent studies have emphasized the relationship between genetic variants of CD33 and the effectiveness of GO in patients with acute myeloid leukemia." (PMID 38255313, 2024). "In the myeloid space, the anti-CD3/CD33 Duobody JNJ-67571244 is in phase 1 testing for r/r acute myeloid leukemia (AML) and high-risk myelodysplastic syndromes (MDS) (NCT03915379)." (PMID 34073188, 2021). "Currently, CD16 × IL-15 × CD33 TriKE is being evaluated in phase I and II clinical trials in patients with advanced systemic mastocytosis, refractory/relapsed acute myeloid leukemia, or CD33-expressing high-risk myelodysplastic syndromes (NCT03214666)." (PMID 32140153, 2020). "With a commercial trade name of Mylotarg, this chemical conjugate consists of an anti-CD33 antibody linked with calicheamicin, a drug of high systemic toxicity for the treatment of acute myeloid leukemia (AML)." (PMID 31091786, 2019). "In particular, a decline in DC/MC of the myeloid lineage (CD33+/CD34+) is associated with disease relapse: in patients transplanted for acute myeloid leukemia (AML) and myelodysplastic syndrome (MDS), CD34+ PBMC MC was found to be an independent predictor of relapse and inferior survival." (PMID 34950586, 2021). "We tested whether a single nucleotide polymorphism (SNP) that affects splicing of CD33 predicted response to treatment in adults with acute myeloid leukemia (AML) who received the novel CD33 antibody-drug conjugate SGN-CD33A." (PMID 31439003, 2019). "CD33 has been associated previously with acute myeloid leukaemia in humans." (PMID 27228113, 2016). "The CD33 rs12459419 (C>T; Ala14Val) single-nucleotide polymorphism (SNP) has been reported to modulate treatment response and survival in pediatric patients with acute myeloid leukemia (AML) receiving gemtuzumab ozogamicin (GO), an anti-CD33 antibody linked to the cytotoxic compound calicheamicin." (PMID 42123630, 2026). "These agents bind simultaneously to tumor-associated antigens, such as CD33 in acute myeloid leukemia (AML), and CD3 on T cells, facilitating robust T-cell-mediated cytotoxicity." (PMID 39982231, 2025). "The CD33 gene encodes a differentiation antigen of acute myeloid leukemia (AML) progenitor cells and is a very well‐known pathological marker of AML." (PMID 32207560, 2020). "We genetically modified human activated T-cells from healthy donors or patients with acute myeloid leukemia with retroviral supernatant encoding the inducible Caspase9 suicide gene, a ΔCD19 selectable marker, and a humanized third generation chimeric antigen receptor recognizing human CD33." (PMID 27907031, 2016). "Consistent with its characteristic as a myeloid differentiation antigen, CD33 is expressed on at least a subset of malignant blasts in nearly all patients with acute myeloid leukemia (AML) and also, perhaps, in underlying leukemia stem cells in some cases." (PMID 27248327, 2016). "Mylotarg® (gemtuzumab ozogamicin) was the first ADC to be approved in 2000 for the treatment of acute myeloid leukemia (AML) and was composed of a CD33-targeted antibody linked to the cytotoxic drug calicheamicin via an acid-labile hydrazone linker." (PMID 25446773, 2015). "Cases of acute leukemia with ≥2 myeloid-associated markers, such as CD13, CD33, and CD117, are considered acute myeloid leukemia with minimal differentiation." (PMID 40227608, 2025).
acute myeloid leukemia (continued). "While 100,000 copies of CD20 were considered sufficient to effectively treat non-Hodgkin’s lymphoma with the anti-CD20 antibody rituximab, only 5000–10,000 copies of CD33 were needed to treat acute myelogenous leukemia with MylotargTM, an anti-CD33 ADC." (PMID 40005994, 2025). "Antibody–drug conjugates (ADCs) have long been pursued to improve cure rates in these malignancies, with a major focus on CD33 (for acute myeloid leukemia [AML]) and CD22 (for B-acute lymphoblastic leukemia [B-ALL])." (PMID 41514580, 2025). "The field reached its first regulatory milestone in 2000 with the FDA approval of gemtuzumab ozogamicin (Mylotarg®), an anti-CD33 ADC for acute myeloid leukemia, which used a hydrazone linker to connect a humanized mAb to the DNA-damaging agent calicheamicin." (PMID 41012501, 2025). "This approach was demonstrated by developing CAR-T cells with SdAbs against CD33, a target for acute myeloid leukemia (AML)." (PMID 40084273, 2025). "In the context of MRD, current lines of investigation to eliminate MDSCs are firstly the CD33 targeted antibody-conjugate gemtuzumab ozogamicin is approved for use in patients with CD33+ acute myeloid leukaemia." (PMID 41373503, 2025). "For example, using a 4-1BB-based CAR to engineer dendritic cells, researchers have shown that these CAR-DCs can produce IL-12, enhancing the effectiveness of anti-CD33 CAR-T-cell therapy for acute myeloid leukemia (AML)." (PMID 40481182, 2025). "The launch of gemtuzumab ozogamicin in 2000 for CD33-positive acute myeloid leukemia (AML) marked the beginning of the ADC development." (PMID 40430899, 2025). "In 2018, Chinese researchers reported the first Phase I/II clinical trial (NCT02944162) of CD33 CAR-NK cells for the treatment of relapsed/refractory acute myeloid leukemia (AML)." (PMID 40852706, 2025). "In acute myeloid leukemia, the most commonly investigated targets in the experimental setting include CD33 and CD146." (PMID 41514545, 2025). "Among them, gemtuzumab ozogamicin (GO), the first approved antibody-drug conjugate (ADC), has revolutionized the treatment landscape of CD33-positive acute myeloid leukemia." (PMID 41020214, 2025). "In 2000, under an accelerated approval process, the US FDA approved the first ADC, Mylotarg (gemtuzumab ozogamicin), which targets CD33 for the treatment of relapsed acute myeloid leukemia (AML)." (PMID 40514426, 2025). "Gemtuzumab ozogamicin (GO) is an ADC targeting the CD33 antigen and is approved for the treatment of acute myeloid leukemia (AML)." (PMID 41471096, 2025). "In the preclinical studies, BiKE has been effectively used to target CD19/CD22 on B cell non-Hodgkin's lymphoma, CD33 on acute myeloid leukemia (AML) and myelodysplastic syndromes (MDS), EpCAM on various carcinomas, and CD133 on cancer stem cells." (PMID 39415291, 2024). "CD33 is a myeloid differentiation antigen expressed on acute myeloid leukemia cells and a therapeutic drug target." (PMID 39316441, 2024). "GO, Mylotarg, GO Resistance, CD33, Gemtuzumab Toxicity, Gemtuzumab Leukemia, and Acute Myeloid Leukemia were the keywords and subject headings investigated in all the investigations." (PMID 38255313, 2024). "Research in the lab has demonstrated that CAR T cells targeting either CD123 or CD33 can reduce cases of acute myeloid leukemia (AML)." (PMID 39127974, 2024). "An actinium-225 conjugated anti-CD33 antibody lintuzumab has been tested in patients with acute myeloid leukemia with safety and some extent of efficacy in a phase I trial." (PMID 39596031, 2024). "For example, Mylotarg (Gemtuzumab Ozogamicin), which was initially approved for the treatment of CD33-positive acute myeloid leukemia (AML) in 2001, withdrew from the market in 2010 due to severe toxicity." (PMID 39060958, 2024).
acute myeloid leukemia (continued). "Currently, there are 11 ADCs approved by FDA covering indications such as CD33-positive acute myeloid leukaemia, HER2-positive metastatic breast cancer, locally advanced or metastatic urothelial cancer, large B-cell lymphoma." (PMID 39744013, 2024). "Gemtuzumab ozogamicin, as the first ADCs approved by the FDA, was indicated for the treatment of first-relapsed acute myeloid leukemia (AML) in patients aged 60 years or older who are CD33 positive and unsuitable for cytotoxic chemotherapy." (PMID 38665947, 2024). "Low-nanomolar rapamycin concentration regulates the heterodimerization of CD33-specific DARIC T cells in preclinical models of acute myeloid leukemia." (PMID 38502193, 2024). "In recent decades, antibody-drug conjugates (ADCs) have made encouraging progress since the first approval of gemtuzumab ozogamicin (Mylotarg®) for the treatment of CD33-positive acute myeloid leukaemia (AML) patients." (PMID 39744013, 2024). "Three primary inclusion criteria were used to select the articles: (i) studies on global oncology, (ii) gemtuzumab resistance and toxicity, and (iii) CD33 and acute myeloid leukemia." (PMID 38255313, 2024). "Gemtuzumab ozogamicin was the first ADC approved in 2000 by the FDA for the treatment of CD33-positive acute myeloid leukemia (AML)." (PMID 38429828, 2024). "The first approval of an ADC for cancer treatment occurred in 2000 when Gentuzumab ozogamicin, an anti-CD33 mAb-calicheamicin conjugate, was introduced for the treatment of relapsed CD33+ acute myeloid leukemia (AML)." (PMID 39796075, 2024). "Gemtuzumab ozogamicin (GO), a CD33-targeting antibody drug conjugate, previously showed longer relapse-free survival when combined with induction chemotherapy in patients with favorable-risk acute myeloid leukemia (AML)." (PMID 39062189, 2024). "GO was re‐approved in 2017, at a threefold lower dose that improved tolerability in CD33‐positive acute myeloid leukaemia (AML) or relapsed/refractory AML patients." (PMID 38963257, 2024). "FDA approved the first ADC, gemtuzumab ozogamicin, for the treatment of relapsed or refractory CD33-positive acute myeloid leukemia (AML) in 2000." (PMID 38966176, 2024). "Studies have demonstrated that CD33, a myeloid differentiation antigen, is highly expressed in acute myeloid leukaemia progenitor cells, but it also can be detected in normal haematopoietic stem cells." (PMID 38712978, 2024). "Gemtuzumab ozogamicin (Wyeth/Pfizer) received accelerated approval for relapsed CD33+ acute myeloid leukemia (AML) in 2000 but was voluntarily withdrawn from the market in 2010 after post-marketing studies." (PMID 38766629, 2024). "Val-ILs loaded with an antibody against CD33, at a dose of 4000 particles per cell, also demonstrated efficient alterations in the viability of two acute myeloid leukemia (AML) cell lines, HL60 (68% decrease, P < 0.0001) and THP1 (100% decrease, P < 0.0001)." (PMID 38734740, 2024). "After adjusting the dosage and conducting numerous clinical trials, Gemtuzumab ozogamicin was reapproved by the FDA in 2017 for use in newly diagnosed and relapsed/refractory CD33-positive acute myeloid leukemia patients." (PMID 38173833, 2023). "Lintuzumab is a humanized monoclonal antibody that targets CD33, which is expressed in a subset of lymphoid neoplasms such as acute myeloid leukemia (AML) as well as multiple myeloma." (PMID 37511386, 2023). "The first-in-class ADC to be FDA-approved for therapy was gemtuzumab ozogamicin (Mylotarg), in 2000 for the treatment of CD33-positive acute myeloid leukemia (AML)." (PMID 37841262, 2023). "Of note nowadays, therapeutic antibodies targeting the V-set domain or sialic acid-binding domain of CD33 have been approved to treat acute myeloid leukemia." (PMID 37506557, 2023). "The use of CD33 monoclonal antibodies was previously studied in acute myeloid leukemia and in hepatitis B infection." (PMID 37506557, 2023).
acute myeloid leukemia (continued). "For the treatment of hematogenous tumors, CD33 is the most well-studied target for acute myeloid leukemia (AML)-specific CAR T cells." (PMID 37367867, 2023). "For instance, Mylotarg, used in relapsed acute myeloid leukemia, features a CD33 antibody comprising an acid-sensitive cleavable linker and a DNA-damaging agent (N-acetyl-γ-calicheamicin)." (PMID 37987250, 2023). "This is an open-label, Phase I study of QN-023a (allogeneic CAR-NK cells targeting CD33) in relapsed/refractory Acute Myeloid Leukemia (AML)." (PMID 37654497, 2023). "Early studies with gemtuzumab ozogamicin (GO), a humanized anti-CD33 mAb linked to the DNA-binding cytotoxin calicheamicin, showed single-agent activity in refractory pediatric and adult patients with acute myeloid leukemia (AML) (28–30% overall response)." (PMID 37509390, 2023). "This study used a humanized anti-CD33 monoclonal antibody (HuM195) conjugated to the alpha-emitting isotope 213Bi to specifically target myeloid leukemia cells in patients who had acute myelogenous leukemia (AML) or chronic myelomonocytic leukemia." (PMID 37444603, 2023). "Mylotarg (gemtuzumab ozogamicin), a CD33-targeted monoclonal antibody conjugated with cytotoxic drug calicheamicin, was approved for CD33-positive acute myeloid leukemia (AML) treatment." (PMID 36354547, 2022). "Currently, in the UK, it is licenced in the treatment of CD33-positive acute myeloid leukaemia for people aged 15 and over." (PMID 36498915, 2022). "CD33 is also an attractive therapeutic target for acute myeloid leukemia (AML) and neurodegenerative disorders." (PMID 35454108, 2022). "The first clinical trial results regarding CAR-NK-92 targeting the CD33 antigen on human relapsed and refractory acute myeloid leukemia (AML) cells were reported in 2018." (PMID 36612114, 2022). "Several studies have developed NPs functionalized with a mAb targeting Siglec-3 (CD33), which is abundantly expressed on the surface of acute myeloid leukaemia cells." (PMID 35205658, 2022). "It consists of a humanised IgG4 mAb conjugated to a calicheamicin payload that targets the CD33 surface antigen, which is present in 85–90% of individuals with acute myeloid leukaemia." (PMID 35964048, 2022). "HUM-195/rGEL has been shown to be highly effective at selectively killing a CD33+ acute myeloid leukaemia (AML) cell line both in vitro and in vivo in an animal model of AML." (PMID 36006226, 2022). "Based on similar results, it has been reported that decitabine co-treatment with CD33-CAR-T cell increased the tumor cell eradication by upregulating the CD33 expression level on acute myeloid leukemia (AML) cell lines." (PMID 36419058, 2022). "The FDA approved the first ADC drug, a conjugate of an anti-CD33 monoclonal antibody and calicheamicin, Gemtuzumab ozogamicin (GO), for the treatment of patients aged > 60 years with relapsed CD33-positive acute myeloid leukemia (AML) in 2000." (PMID 36418786, 2022). "A clinical trial of autologous CAR-T therapy targeting CD33 was conducted in a 41-year-old man with acute myeloid leukemia (NCT01864902)." (PMID 36232824, 2022). "GO was approved in 2017 by the FDA and in 2018 by the EMA in addition to standard chemotherapy with daunorubicin and cytarabine in patients with de novo CD33-positive acute myeloid leukemia with additional approval in the r/r setting as monotherapy by the FDA." (PMID 35406464, 2022). "Gemtuzumab ozogamicin, an FDA approved CD33-targeted medication for the treatment of relapsed and/or refractory acute myeloid leukemia (R/R) has been withdrawn from the market due to unfavorable adverse effects (AE)." (PMID 35964048, 2022). "Myeloid cell surface antigen CD33 is a single-pass type I transmembrane protein receptor expressed on malignant bast cells in the majority of acute myeloid leukaemia cases." (PMID 36498915, 2022). "Some examples of tumour-specific cell surface proteins include HER2 (breast cancer), CD30 (lymphomas) and CD33 (acute myeloid leukaemia)." (PMID 34063364, 2021).